RAB38 (RAB38, member RAS oncogene family)
Description:
The small GTPases Rab are key regulators of intracellular membrane trafficking, from the formation of transport vesicles to their fusion with membranes. Rabs cycle between an inactive GDP-bound form and an active GTP-bound form that is able to recruit to membranes different sets of downstream effectors directly responsible for vesicle formation, movement, tethering and fusion (By similarity). RAB38 may be involved in melanosomal transport and docking. Involved in the proper sorting of TYRP1. Involved in peripheral melanosomal distribution of TYRP1 in melanocytes; the function, which probably is implicating vesicle-trafficking, includes cooperation with ANKRD27 and VAMP7 (By similarity). Plays a role in the maturation of phagosomes that engulf pathogens, such as S.aureus and M.tuberculosis. Plays an important role in the control of melanin production and melanosome biogenesis. In concert with RAB32, regulates the proper trafficking of melanogenic enzymes TYR, TYRP1 and DCT/TYRP2 to melanosomes in melanocytes (By similarity).
Synonyms: NY-MEL-1; rrGTPbp
Tractability: Small molecule: a structure with a bound ligand is known. Antibody: UniProt places it where antibodies can reach, with high confidence; its Gene Ontology location is reachable by antibodies, with medium confidence. PROTAC: its protein half-life has been measured.
Gene: Protein-coding gene on chromosome 11 (88,113,251 to 88,175,443, reverse strand). Ensembl gene ENSG00000123892.
Subcellular location: Cell membrane; Melanosome; Cytoplasmic vesicle, phagosome; Cytoplasmic vesicle, phagosome membrane; Melanosome membrane
Pathways (Reactome):
Metabolism of proteins: RAB geranylgeranylation
Vesicle-mediated transport: RAB GEFs exchange GTP for GDP on RABs
Gene Ontology:
Molecular function: AP-1 adaptor complex binding; AP-2 adaptor complex binding; AP-3 adaptor complex binding; BLOC-2 complex binding; GTP-dependent protein binding; protein binding; G protein activity; GTP binding; GTPase activity
Biological process: endosome to melanosome transport; melanosome assembly; mitochondrion organization; phagosome acidification; protein localization to membrane; melanosome organization; protein transport; small GTPase-mediated signal transduction; eye pigmentation; intercellular transport; platelet dense granule organization; positive regulation of melanin biosynthetic process; positive regulation of phosphatidylcholine biosynthetic process; positive regulation of protein localization to cell periphery; vesicle-mediated transport
Cellular component: early endosome; early endosome lumen; lysosome; melanosome; melanosome membrane; membrane; mitochondria-associated endoplasmic reticulum membrane contact site; mitochondrion; phagocytic vesicle; cytosol; trans-Golgi network; cell body; cytoplasmic vesicle; Golgi apparatus; perinuclear region of cytoplasm; phagocytic vesicle membrane; plasma membrane; vesicle
Genetic constraint (gnomAD): Loss-of-function variants: 15 observed, 19.42 expected, observed/expected ratio (o/e) 0.77, 90% interval 0.52 to 1.19. The upper end of that interval is the gene's LOEUF score, 1.19, which puts it in group 5 of 6, group 1 being the genes least tolerant of losing a copy. Missense variants: 294 observed, 283.41 expected, observed/expected ratio (o/e) 1.04, 90% interval 0.94 to 1.14. Synonymous variants: 101 observed, 111.15 expected, observed/expected ratio (o/e) 0.91, 90% interval 0.77 to 1.07.
Homologues: Orthologues: chimpanzee RAB38 (100% identical), macaque RAB38 (99% identical), mouse Rab38 (97% identical), dog RAB38 (97% identical), guinea pig RAB38 (96% identical), pig RAB38 (96% identical), rat Rab38 (96% identical), tropical clawed frog rab38 (82% identical), zebrafish rab38b (74% identical). Paralogues in human: RAB32 (66% identical), RAB29 (52% identical), RAB10 (36% identical), RAB13 (36% identical), RAB35 (36% identical), RAB7A (36% identical), RAB1A (33% identical), RAB22A (33% identical), RAB6B (33% identical), RAB8B (33% identical), RAB15 (32% identical), RAB19 (32% identical), and 56 more.
Diseases named in the same sentence as RAB38 in open-access papers:
RAB38 is named in the same sentence as 40 diseases in open-access papers, as found by Europe PMC text mining. Sharing a sentence is not in itself a finding about the gene and the disease. The quoted sentences say what the papers report.
melanoma (11 papers, 2017 to 2025). A malignant, usually aggressive tumor composed of atypical, neoplastic melanocytes. "In B16-F10 mouse melanoma cells, Rab38 drives LRRK2 membrane association and overexpressed kinase-active LRRK2 shows striking pericentriolar recruitment, which is dependent on the presence of endogenous Rab38 but not Rab32 or Rab29." (PMID 37625589, 2023). "Considering the role of these proteins in melanoma invasion and the observation that RAB27A and RAB38 expression were associated with shorter OS of melanoma patients, these GTPases were proposed as drivers of melanoma metastasis." (PMID 33072757, 2020). "For example, in the field of cancer research, it has been used to model the RAB38 protein (Ras related protein 38), relevant in melanoma and RASSF2 (Ras Association Domain Family Member 2), studied in different tumor types." (PMID 30340325, 2018). "Rab38 is highly expressed in melanoma and causes specific antibody response in melanoma patients." (PMID 30060521, 2018). "Upregulated expression of some endosomal–lysosomal-associated genes controlling melanogenesis (e.g., RAB32, RAB38, RAB27A, and RAB33) has been observed in melanoma cells and melanoma patient samples." (PMID 41155412, 2025). "Rab38 knockdown decreased LRRK2 membrane association in melanocytes and disrupted pericentriolar recruitment of overexpressed LRRK2 in B16-F10 melanoma cells." (PMID 37625589, 2023). "Based on this, RAB27A and RAB38 were found upregulated in metastatic melanoma, relative to the matched primary melanoma cell lines derived from human samples." (PMID 33072757, 2020). "On the other hand, RAB38 regulates melanoma cell invasion by increasing the expression and activity of two MMPs, MMP-2 and -9." (PMID 33072757, 2020). "Silencing of the BLOC-3 subunits Hps1 and Hps4 results in the mislocalization of Rab32 and Rab38 and a reduction in pigmentation in a melanoma cell line." (PMID 28438206, 2017). "Rab38 may serve as a novel biomarker and potential prognostic indicator for melanoma and other malignancies." (PMID 40977744, 2025). "Later, Rab38 was also isolated from a human melanoma cDNA library." (PMID 30060521, 2018). "Rab38 but not Rab32 or Rab29 drives pericentriolar recruitment of exogenous kinase-active LRRK2 in B16 melanoma cells." (PMID 37625589, 2023). "In contrast, B16-F10 mouse melanoma cells (“B16 cells”) produce melanosomes, indicating that pathways of LRO biogenesis are active and express high levels of endogenous Rab32, Rab38, and LRRK2." (PMID 37625589, 2023). "These genes along with their activation values Eq for melanoma (MEL) are, GPNMB (MEL activation = 18.59), UBL3 (MEL activation = 1.39), AP1S2 (MEL activation = 1.28), RAB38 (MEL activation = 0.91), EDNRB (MEL activation = 0.55), JUN (MEL activation = 0.34), and C1orf21 (MEL activation = -0.13)." (PMID 34570764, 2021). "Notably, the melanosome protein Rab38 was exclusively present in melanoma EVs while absent in healthy donor EVs." (PMID 38353833, 2024). "In addition, melanoma cells typically display enhanced secretion activity of extracellular vesicles (EVs) and melanosomes, which may be significantly augmented by the upregulation of RAB27A, RAB32, RAB33A, and RAB38." (PMID 41155412, 2025).
Hermansky-Pudlak syndrome (5 papers, 2007 to 2023). Hermansky-Pudlak syndrome (HSP) is a multi-system disorder characterized by oculocutaneous albinism, bleeding diathesis and, in some cases, neutropenia, pulmonary fibrosis, or granulomatous colitis. "Ruby rats carrying Rab38 and other gene mutations exhibit oculocutaneous albinism, bleeding diathesis, and hence, are a rat model of human Hermansky-Pudlak syndrome (HPS)." (PMID 28438206, 2017). "Rab38-deficient rats are a rat model of genetically heterogeneous Hermansky-Pudlak syndrome (HPS), which is clinically characterized by oculocutaneous albinism, bleeding diathesis, and in the majority of cases fatal interstitial pneumonia." (PMID 28438206, 2017). "Furthermore, it has been reported that Rab38-deficient rats serve as a model for Hermansky-Pudlak syndrome, a prenylation deficiency disease showing a similar phenotype as seen in humans affected by this disease." (PMID 24358126, 2013). "Rab38 is the gene responsible for Hermansky-Pudlak syndrome (HPS), in which defective biogenesis of LROs results in an abnormal pulmonary phenotype, predisposition to hemorrhage, and oculocutaneous albinism." (PMID 37793839, 2023). "Furthermore, it has been shown that the Rab38 gene is mutated in ruby rats, a strain characterized by hypopigmentation and platelet storage pool deficiency related to Hermansky-Pudlak syndrome (HPS)." (PMID 26818140, 2016). "Interestingly, two genes associated with the Hermansky-Pudlak syndrome, HPS3 and Rab38, a small GTPase of the Rab family expressed in bronchial and alveolar epithelial cells, were increased in the “rapid” progressors group." (PMID 17534432, 2007).
bladder cancer (3 papers, 2021 to 2024). "RAB38 has been previously noted to be an important factor in melanogenesis and a driver of malignant progression of pancreatic and bladder cancer." (PMID 34209035, 2021). "The top 20 downregulated genes included RAB38 (a GTPase of the Ras superfamily that promoted cell proliferation in human bladder cancer cells) and LUZP6 (a cryptic tumor antigen that triggered antitumor immune responses in patients with myeloproliferative diseases)." (PMID 38673926, 2024).
oculocutaneous albinism (3 papers, 2017 to 2022). Oculocutaneous albinism (OCA) describes a group of inherited disorders of melanin biosynthesis characterized by a generalized reduction in pigmentation of hair, skin and eyes and variable ocular findings including nystagmus, reduced visual acuity and photophobia. "A study reported that mutations in Rab38 are responsible for the diluted coat colour and oculocutaneous albinism phenotype." (PMID 36471254, 2022). "Since Rab38 mutation appears to cause oculocutaneous albinism, bleeding diathesis, and lung abnormalities, it is expected that appropriate exogenous expression of Rab38 in the lungs will restore ameliorated homeostasis of lung surfactant." (PMID 28438206, 2017). "Hence, it is likely that, in addition to oculocutaneous albinism, a platelet pool storage deficiency leading to a bleeding diathesis is caused by a complete deficit of Rab38." (PMID 30060521, 2018). "Moreover, it is likely that the mutation in the chocolate locus might also cause lung disease, as well as oculocutaneous albinism, as high expression of the Rab38 mRNA and encoded protein was observed in both the skin and the lung tissues." (PMID 30060521, 2018).
choroideremia (2 papers, 2013 to 2024). Choroideremia (CHM) is an X-linked chorioretinal dystrophy characterized by progressive degeneration of the choroid, retinal pigment epithelium (RPE) and retina. "They found that Rab38, Rab27a, Rab27b, and Rab42 are prenylated the slowest and concluded that this finding may implicate them in choroideremia, since they may be more impacted by REP-1 deficiency when only REP-2 is present." (PMID 38920696, 2024). "Our work points to possible contribution of Rab38 to the emergence of choroideremia in addition to Rab27a and Rab27b." (PMID 24358126, 2013). "In conclusion, Rab27a is prenylated slowly in vivo and in vitro, but in addition also other Rabs like Rab38 and Rab42 show slow prenylation kinetics and could therefore potentially play a role in choroideremia." (PMID 24358126, 2013). "In choroideremia patients, Rab38 could remain in an unprenylated and therefore non-functional state, causing similar eye defects observed in the mouse model and thus resulting in impaired vision." (PMID 24358126, 2013).
diabetes (2 papers, 2019 to 2020). "Previous meta-analysis of GWAS demonstrated that variation of RAB38/CTSC was highly associated with UACR of European ancestry with diabetes." (PMID 33096837, 2020). "In addition, variants in HS6ST1 and near RAB38/CTSC were implicated in albuminuria in patients with diabetes." (PMID 30900988, 2019).
glioma (2 papers, 2021 to 2022). A benign or malignant brain and spinal cord tumor that arises from glial cells (astrocytes, oligodendrocytes, ependymal cells). "We interrogated the TCGA database to assess the prognostic impact of high levels of RAB38 mRNA in glioblastoma patients and patients with low-grade gliomas." (PMID 34209035, 2021). "When comparing low-grade gliomas to glioblastomas, the latter demonstrated significantly higher RAB38 expression." (PMID 34209035, 2021). "Despite the evidence that RAB38 is upregulated in gliomas, the functional significance of RAB38 in glioblastoma growth and protection from cell death has not been elucidated." (PMID 34209035, 2021). "When comparing low-grade gliomas to glioblastomas, the latter demonstrated significantly higher RAB38 expression, which led to our use of the glioblastoma cell lines LN229, T98G, and the patient-derived GBM43 line." (PMID 34209035, 2021). "Furthermore, high expression of RAB38 in low-grade gliomas is correlated with a poor prognosis." (PMID 34209035, 2021). "Interestingly, RAB38, a new member of the RAB small G protein family that regulates intracellular vesicle trafficking, RAB27a, as well as RAB34 have all been reported to confer a poor prognosis, associated with malignant progression and subtype preference in gliomas." (PMID 36430705, 2022). "Despite evidence that RAB38 is upregulated in gliomas and correlated with a poor prognosis, the functional significance of RAB38 in glioblastoma growth and proliferation has not been studied prior to this investigation." (PMID 34209035, 2021).
Hypertension (2 papers, 2021 to 2024). The presence of chronic increased pressure in the systemic arterial system. "More than 50 genetic variants have been identified that are potentially associated with the decline of kidney function and the development of hypertension and renal injury in various studies, among which the most frequently identified gene variants are UMOD, MYH9, APOL1, SHROOM3, RAB38, and DAB2." (PMID 33377622, 2021).
Parkinson disease (2 papers, 2023). A progressive degenerative disorder of the central nervous system characterized by loss of dopamine producing neurons in the substantia nigra and the presence of Lewy bodies in the substantia nigra and locus coeruleus. "Together with Rab38/38 and the retromer complex, this interaction regulates signaling pathways associated with LRRK2 activation; furthermore, a missense mutation of Rab32 has been linked with Parkinson’s disease (PD)." (PMID 37566051, 2023). "In mouse melanocytes, which express high levels of Rab38, Rab32, and Rab29, knockdown (or CRISPR knockout) of Rab38, but not Rab32 or Rab29, decreases phosphorylation of multiple LRRK2 substrates, including Rab10 and Rab12, by both endogenous LRRK2 and exogenous Parkinson’s disease-mutant LRRK2." (PMID 37625589, 2023).
autism (1 paper, 2016). Persistent deficits in social interaction and communication and interaction as well as a markedly restricted repertoire of activity and interest as well as repetitive patterns of behavior. "In more detail, we found one Rab32 always coupled with the melanoma oncogene Grm1, while one Rab38 is always close to Grm5, a gene playing a fundamental role in many human disorders such as schizophrenia and autism." (PMID 26818140, 2016).
chordoma (1 paper, 2014). Chordomas are rare malignant tumors arising from embryonic remnants of the notochord in axial skeleton. "We demonstrate the expression of new potential candidates for chordoma tumorigenesis, such as CD24, ECRG4, RARRES2, IGFBP2, RAP1, HAI2, RAB38, osteopontin, GalNAc-T3, VAMP8 and others." (PMID 24452533, 2014).
Diabetic Nephropathy (1 paper, 2020). "The findings confirmed the roles of gender and variants of RAB38 in the risk of UPCR in Diabetic Nephropathy patients." (PMID 33096837, 2020).